WDR17 (WD repeat domain 17)
Tractability: PROTAC: ubiquitination databases record sites on it.
Gene: Protein-coding gene on chromosome 4 (176,065,840 to 176,182,820, forward strand). Ensembl gene ENSG00000150627.
Subcellular location (Human Protein Atlas): Nuclear speckles
Genetic constraint (gnomAD): Loss-of-function variants: 119 observed, 139.27 expected, observed/expected ratio (o/e) 0.85, 90% interval 0.74 to 1. The upper end of that interval is the gene's LOEUF score, 1, which puts it in group 4 of 6, group 1 being the genes least tolerant of losing a copy. Missense variants: 1,348 observed, 1,457.8 expected, observed/expected ratio (o/e) 0.92, 90% interval 0.88 to 0.97. Synonymous variants: 487 observed, 500.74 expected, observed/expected ratio (o/e) 0.97, 90% interval 0.9 to 1.05.
Homologues: Orthologues: chimpanzee WDR17 (99% identical), macaque WDR17 (98% identical), rabbit WDR17 (92% identical), pig WDR17 (91% identical), dog WDR17 (90% identical), mouse Wdr17 (89% identical), rat Wdr17 (88% identical), tropical clawed frog wdr17 (86% identical), zebrafish wdr17 (82% identical), guinea pig WDR17 (74% identical). Paralogues in human: TEP1 (16% identical), WDR7 (11% identical), WDR62 (9% identical), MAPKBP1 (9% identical), POC1B (9% identical), AHI1 (8% identical), POC1A (8% identical), WDR5 (7% identical), WDR81 (7% identical), NWD1 (7% identical), WDR5B (7% identical), WDR27 (7% identical), and 14 more.
Diseases named in the same sentence as WDR17 in open-access papers:
WDR17 is named in the same sentence as 8 diseases in open-access papers, as found by Europe PMC text mining. Sharing a sentence is not in itself a finding about the gene and the disease. The quoted sentences say what the papers report.
retinal diseases (2 papers, 2004 to 2009). "We demonstrate that variation in rhodopsin expression efficiently predicts candidate genes for eight uncloned retinal diseases, including WDR17 for the human RP29 locus." (PMID 19727342, 2009). "In many instances, this results in a significant reduction of genes in the respective intervals offering a manageable number of candidates for retinal diseases (e.g. the RP29 locus contains 28 SGPs of which 5 are present in the reference retinome including GPM6A, WDR17, FLJ22649, VEGFC, AGA)." (PMID 15283859, 2004).
retinitis pigmentosa (2 papers, 2017 to 2023). Retinitis pigmentosa (RP) is an inherited retinal dystrophy leading to progressive loss of the photoreceptors and retinal pigment epithelium and resulting in blindness usually after several decades. "Additionally, WDR17 was found among genes correlating with rhodopsin expression and mapped to human loci associated with retinitis pigmentosa." (PMID 37172722, 2023). "Wdr17 is a candidate for the RP29 form of Retinitis Pigmentosa and has binding sites for CRX and NRL close to the rod TSS." (PMID 28640837, 2017).
anal carcinoma (1 paper, 2021). "A cross‐sectional series of 176 tissue samples of anal cancer, AIN3, AIN2, AIN1 and control biopsies obtained in HIV‐negative women and men was tested for six methylation markers (ASCL1, LHX8, SST, WDR17, ZIC1 and ZNF582)." (PMID 33580586, 2021).
colorectal cancer (1 paper, 2025). A primary or metastatic malignant neoplasm that affects the colon or rectum. "WDR17 encodes the WD repeat-containing protein 17; however, this is the first report linking its methylation to colorectal cancer." (PMID 40943367, 2025).
infertile (1 paper, 2024). "Germ cell-deficient infertile mouse models had significantly reduced Wdr17 expression." (PMID 38791636, 2024).
cancer (2 papers, 2015 to 2023). A tumor composed of atypical neoplastic, often pleomorphic cells that invade other tissues. "Mutations in RUNX1T1 (encoding cyclin-D-related protein, a transcriptional regulator) and WDR17 (WD repeat-containing protein 17) were identified in 3 patient samples in the cohort and predicted to be likely cancer driver mutations impacting protein function by all 4 algorithms." (PMID 26536348, 2015).
WDR17 also shares sentences with these, for which no sentence is quoted: Joubert syndrome (1 paper); metastatic prostate carcinoma (1).